TRPM8 (transient receptor potential cation channel subfamily M member 8)
Diseases named in the same sentence as TRPM8 in open-access papers (continued):
Sharing a sentence is not in itself a finding about the gene and the disease.
tumor (continued). "Our recent discovery showed that TRPM8 is aggressively targeted for degradation in PC, while recovery of the protein effectively suppressed tumor cells growth." (PMID 28039451, 2017). "Remarkably, we detected that TRPM8 expression profile is strongly altered in the tumor tissues in comparison to the healthy individuals." (PMID 28039451, 2017). "In particular, expression of TRPM8 in breast carcinoma correlates with the histological grade, Ki-67, tumor size and expression of the estrogen receptor." (PMID 27289382, 2016). "Results of these studies support important roles of TRPM8 channels in epithelial-mesenchymal transformation and tumor metastasis." (PMID 26512697, 2015). "Recent reports have begun to reveal the signaling mechanisms that mediate the biological roles of TRPM8 in tumor growth and metastasis." (PMID 26512697, 2015). "Clinicopathological analysis has shown that over-expression of TRPM8 correlates with tumor progression." (PMID 26512697, 2015). "Current evidence suggests that TRPM8 channels play contributory roles in tumor growth and metastasis." (PMID 26512697, 2015). "To achieve a more direct correlation between TRPM8 expression and tumor cell proliferation, we used siRNA against TRPM8 and measured its effects on proliferation and cell cycle distribution in the three tumor prostatic cell lines and the non-tumoral one." (PMID 23251635, 2012). "The experiments described so far support the notion that TRPM8 expression occurs both in normal prostate and tumor cells." (PMID 23251635, 2012). "We have used two recently described and highly specific blockers, AMTB and JNJ41876666, and RNAi to determine the relevance of TRPM8 expression in the proliferation of non-tumor and tumor cells." (PMID 23251635, 2012). "Notably, genes associated with metastasis, such as MMP2 and FAP, were upregulated in TRPM8 KO samples, indicating a potential role for TRPM8 in inhibiting tumor invasion." (PMID 40214455, 2025). "Furthermore, given that microglia in the brain also express TRPM8, utilizing Menthol to target microglia and promote immune responses within the tumor microenvironment represents an emerging therapeutic strategy." (PMID 40535121, 2025). "Moreover, our study demonstrates that AD80 is involved in anti-tumour processes by upregulating the expression of TRPM8." (PMID 39385506, 2024). "Moreover, the inhibitory effects of TRPM8 on TRPV1 have been observed not only in pain-related studies but also in tumor studies." (PMID 38892000, 2024). "TRPM8 was found to be significantly upregulated in HCC tumors, and its expression was positively correlated with tumor abundance and size, while mitochondrial size and relative nucleoli abundance were reduced in murine cells with pharmacologically inhibited TRPM8." (PMID 38474168, 2024). "The role of TRPM8 in vivo was evaluated using a mouse subcutaneous xenograft tumour model." (PMID 39385506, 2024). "This study deciphers a novel molecular mechanism of aseptic inflammation in the prostate epithelium caused by the interaction of TRPM8 RNA with TLR3, which exerts a tumor-suppressive role in the prostate by promoting the safeguarding activity of innate immunity." (PMID 38316991, 2024). "Recently, TRPM8 was reported to play an important role in tumour progression." (PMID 39385506, 2024). "This suggests that TRPM8 may facilitate tumor growth by enhancing the Wnt/β-catenin signaling pathway." (PMID 39633507, 2024). "Recently, using the androgen-independent cell line PC3 with stable heterologous expression of TRPM8 channels (PC3-M8), it was reported that TRPM8 activation limited tumor growth by decreasing clonogenicity and cell proliferation through cell cycle arrest at the G0/G1 phase." (PMID 37033630, 2023). "Given that TCAF2 is a binding factor for TRPM8 and can inhibit TRPM8 channel activation in tumor cells, we further evaluated whether TCAF2 exerted similar effects in TPCs." (PMID 37635201, 2023).
tumor (continued). "Next, we investigated the effect of TRPM8 ion channel activity on tumor cell motility." (PMID 37635201, 2023). "To assess tumour cell migration, we first stained the tumour tissue against TRPM8." (PMID 34910361, 2022). "Mechanistically, our in vitro data revealed that the inhibition of tumor growth observed in vivo was accompanied by a reduction in the proliferative cell fraction and increased cell cycle arrest in the G0/G1 phase induced by TRPM8 overexpression." (PMID 35743115, 2022). "However, this percentage of cell cycle arrest is too limited to explain the large difference found in tumor size and volume due to TRPM8 overexpression." (PMID 35743115, 2022). "TRPM8 may thus have different prognostic values in different tumors, and perhaps even between different subtypes of the same tumor." (PMID 35847920, 2022). "It was speculated that TRPM8 might influence tumor progression by interacting with the tumor cell microenvironment." (PMID 36499622, 2022). "Nevertheless, on the basis of these in vivo experiments, we cannot conclude whether TRPM8 overexpression also acts on metastasis dissemination because of the large difference in tumor growth between the PC3 luc and PC3–M8 luc orthotopic grafts." (PMID 35743115, 2022). "Furthermore, it has previously been shown that TRPM8 is also expressed in different ECs and that it is dramatically down-regulated in some tumor-derived ECs, contributing to their more aggressive and pro-angiogenic migratory phenotype." (PMID 35565390, 2022). "However, mutant TRPM8-Y1022F diminished the increase in WT-TRPM8 tumor volumes and weights as well as Ki67 expression." (PMID 35665750, 2022). "Based on this speculation, a series of studies were carried out, trying to investigate the role of TRPM8 in tumor proliferation and migration." (PMID 35361751, 2022). "In AsPC-1 and PANC-1 cells stably expressing WT-TRPM8, control vector, or TRPM8-Y1022F mutant, it was observed that WT-TRPM8 considerably increased tumor cell proliferation and showed a significantly higher migration capacity in PANC-1, compared to control vector-containing cells." (PMID 36844925, 2022). "TRPM8 protein was localized to the plasma membrane of cells in the normal prostate tissue, whereas its channel showed severely internalized pattern of TRPM8 in tumour tissues." (PMID 33617107, 2021). "All datasets depict a high level of heterogeneity of TRPM8 expression between tumors, nevertheless, invariably, the amount of the transcript rises in primary tumor samples compared to benign prostate tissues, to drastically fall in castration resistant metastatic PCa." (PMID 33288740, 2020). "The mechanism of stimulation of tumor growth and metastasis by TRPM8 was actively investigated." (PMID 33344232, 2020). "Since several experiments have correlated ECs contraction with vessel permeability, this study could suggest a protective role of TRPM8 not only in ECs migration, but also in tumor vasculature permeability." (PMID 33132914, 2020). "MS-SPRi results and MOE docking analysis suggest that TRPM8 may be the candidate target of NB as chemosensitizers of DOX for human A549 tumor treatment." (PMID 32929340, 2020). "Afterward, it has been demonstrated that TRPM8 could be detected in a diversity of cell types, including tumor cells." (PMID 31519770, 2019). "In this light, recovery of TRPM8 may pose a novel therapeutic strategy for an anti-tumor defense mechanism." (PMID 28039451, 2017). "These apparently contradictory functions in tumor promotion and suppression suggest that TRPM8 may exert different functions in different tumor entities." (PMID 29221175, 2017). "In this light, testosterone-TRPM8 actions present a tumor suppression mechanism." (PMID 28039451, 2017). "However, functional studies have begun to reveal important roles of TRPM8 ion channels in neoplasia." (PMID 26512697, 2015).
tumor (continued). "These proteins such as the transient receptor melastatin 8 (TRPM8) non-selective cation channel in prostate cancer have been used in clinical trials as tumor-associated antigen for anti-tumor vaccination." (PMID 23966948, 2013). "Furthermore, we detected limited quantitative differences in TRPM8 expression between the tumor cell lines tested (DU145∼LNCaP>PC3), despite their radically different behavior in terms of aggressiveness, proliferation rates and differentiation." (PMID 23251635, 2012). "Because one of the parameters used in the SBR grading system is the cell differentiation, we investigated whether the TRPM8 expression varied with tumour grades." (PMID 20482834, 2010). "We found that TRPM8 over-expression was observed in 77.8% of the ERα positive tumours and in 37.5% of the ERα negative tumours (p < 0.05), suggesting an association between TRPM8 expression and ER+ status." (PMID 20482834, 2010). "Similarly, the aberrant expression of the TRPM8 channel in different types of cancer (prostate, pancreas, breast, lung, colon, and skin) has been correlated with tumor cell progression and migration and with tumor aggressiveness." (PMID 36614186, 2023). "It is thus possible that TRPM8 may promote tumor heterogeneity." (PMID 35847920, 2022). "Interestingly, TRPM8 exerts opposite roles in different tumor cells." (PMID 31519770, 2019). "Therefore, selective targeting of TRPM8 control of TRPV1 responsiveness to transactivation by VEGF may ultimately provide an alternative approach to reduce tumor growth in a clinical setting." (PMID 30483120, 2018). "Although, TRPM8 expression in prostate is androgen and AR-dependent, growing evidence argues for androgen-independent effects, which suggest that TRPM8 expression in these cells may have tumor suppressor functions." (PMID 25980497, 2015). "Furthermore, TRPM8 has even been proposed as a potential target for tumor immunotherapy." (PMID 23251635, 2012). "Finally, we have found a correlation between TRPM8 expression in tumour tissues and ERα expression." (PMID 20482834, 2010). "Specifically, TRPM1 and TRPM2 were upregulated in tumor tissues, whereas TRPM4, TRPM6, TRPM7, and TRPM8 were downregulated in the tumor group." (PMID 41562086, 2025). "Mechanistically, TCAF2 inhibits the expression and activity of TRPM8, leading to Wnt5a secretion in TPCs, which facilitates EMT via the activation of the STAT3 signaling pathway in tumor cells." (PMID 37635201, 2023). "Collectively, these data indicate that TCAF2‐induced Wnt5a secretion through inhibiting TRPM8 in TPCs, which activates the STAT3 signaling pathway in tumor cells, thus facilitating CRCLM." (PMID 37635201, 2023). "Similar to TRPM8, the untreated animals showed an upregulation of BMP2 positivity staining within tumour regions." (PMID 34910361, 2022). "Interestingly, an intriguing association between TRPM8 overexpression and a strong in vivo reduction in VEGF and microvascular density (MVD) has been reported, thus highlighting a possible additional TRPM8–mediated, anti–angiogenic contribution to the observed reduction in tumor growth in vivo." (PMID 35743115, 2022). "We found significantly higher expression levels of TRPA1, TRPM8, and TCAF1/F2 in tumoral tissues compared to normal tissues, but lower expression levels of TRPV6, suggesting that TRP channels have either tumor-suppressive or oncogenic roles." (PMID 36012311, 2022). "Upregulation of Kv11.1 expression was associated with advanced tumor grade and high expression of Ki67 proliferative marker, whereas TRPV6, TRPM8 and AQP1/AQP3 channels were positively correlated with tumor stages III and IV and large tumor size." (PMID 33178018, 2020). "Taken together, functional TRPM8 upregulation in UM 92.1 cells suggests that TRPM8 is a potential drug target for suppressing VEGF induced increases in neovascularization and UM tumor growth since TRPM8 activation blocked VEGF transactivation of TRPV1." (PMID 30483120, 2018).
tumor (continued). "TRPM7 and TRPM8 expression is importantly correlated with the Scarff-Bloom-Richardson (SBR) grade, Ki67 proliferation index, and tumor size." (PMID 29875336, 2018). "Even though such a paradigm exists in various tumor cell types, where C5a plays a complex role in tumor progression and the tumor microenvironment, our results show that C5a induces rises in Ca2+ influx by interacting with TRPV1 and TRPM8." (PMID 39195219, 2024). "Therefore, the regulation mechanism of the TRPM8 ion channel on TRPV1 is of great significance for the suppression of pain and tumor proliferation." (PMID 38892000, 2024). "Exploring the binding site of TCAF2 and TRPM8 would contribute to the development of inhibitors blocking the binding of TCAF2 with TRPM8, as well as to the TPC‐targeting strategy that suppresses tumor hematogenous metastasis through hindering the interaction of TCAF2 and TRPM8 in TPCs." (PMID 37635201, 2023). "In particular, TRPM8 is upregulated in benign hyperplasia (BPH) and during the early androgen-dependent stages of PCa, and then downregulated in the more advanced androgen-independent metastatic stages of the tumor." (PMID 37576340, 2023). "Since TCAF2 inhibited ion channel activity and expression of TRPM8, we further investigated whether TCAF2 induced Wnt5a expression and tumor metastasis via TRPM8." (PMID 37635201, 2023). "TCAF2 is highly expressed in tumor pericytes (TPCs) derived from patients with colorectal cancer liver metastasis (CRCLM), which induces the secretion of Wnt5a through inhibiting TRPM8 channel and activates the STAT3 phosphorylation in tumor cells, thus facilitating CRCLM." (PMID 37635201, 2023). "For this purpose, we assessed the TRPM8 double mutant on two other tumor cell lines that do not express TRPM8 endogenously." (PMID 35565390, 2022). "Targeting the inhibition of the LCK-14-3-3ζ-TRPM8 axis to impair oncogene function of both TRPM8 and LCK may enhance tumor sensitivity to therapeutics, allowing for potential pharmacological targeting for anticancer therapy." (PMID 35665750, 2022). "A study investigating mRNA expression levels of the TRP channels in human CRC tissue versus normal colon mucosa detected an increase in gene expression of TRPM8, TRPV6, and TRPV1 and a lower expression of TRPV4, TRPM4, TRPV3, TRPC6, and TRPV5 in the tumor tissues of CRC compared to normal tissues." (PMID 32182937, 2020). "Finally, we discuss the role of endothelial TRP channels in aberrant tumor vascularization by focusing on TRPC1, TRPC3, TRPV2, TRPV4, TRPM8, and TRPA1." (PMID 32038296, 2019). "With the exception of TRPM8 none of the relevant genes showed a significant association with age, serum PSA concentration, tumor stage, Gleason score or initial metastases at prostatectomy." (PMID 24517338, 2014). "In other words, TRPM8 appears to be required only for tumor cell proliferation and not for normal proliferation." (PMID 23251635, 2012). "TRPM8 was originally thought to be expressed almost exclusively in the prostate and in a number of non-prostatic primary tumours of breast, colon, lung and skin." (PMID 19292918, 2009). "Even though RB cells are non-excitable tumor cells, it is still possible that TRPM8 may exhibit some voltage-sensitive activity." (PMID 38339011, 2024). "In addition, the knockdown of the TRPM8 channel did not affect apoptosis but facilitated the apoptosis induced by the anti-tumor molecule epirubicin (EPI), suggesting a role of the channel in epirubicin resistance." (PMID 37033630, 2023). "Notably, within these early-passage organoids we identified a population fitting our profiling of ERG+ tumor cells, expressing a high level of LE cell markers (KLK3, KLK2, and ACPP) and tumor markers (PCA3, TRPM8, and ERG), which we annotated as putative tumor cells." (PMID 35013146, 2022).
tumor (continued). "As we demonstrated that TRPM8 activation inhibited PCa cell trans–endothelial migration, LNC–WS12s could also represent an efficient strategy to target the extravasation of circulating tumor cells if TRPM8 expression is maintained in these cells." (PMID 35743115, 2022). "Therefore, TRPM8 may be the candidate target of NB in sensitizing cells toward DOX and combating A549 tumor growth." (PMID 32929340, 2020). "Together our studies suggested that TRPM8 is a key element of the orphan pathway of non-genomic testosterone-induced responses, and its activity may significantly contribute to anti-tumor defense mechanism and could serve as a novel therapeutic target." (PMID 28039451, 2017). "Therefore, we can conclude that TRPM8 is not directly involved in the control of cell apoptosis and that the difference observed in the apoptotic fraction ex vivo is instead the result of the normal tumor growth of PC3 with a necrotic area at the center and an apoptotic area next to it." (PMID 35743115, 2022). "Unlike TRPM1 that plays the role of a tumor suppressor gene in melanoma, TRPM7 and TRPM8 are aberrantly expressed in pancreatic, gastric, breast and human head and neck cancers." (PMID 30477473, 2018). "The cold-temperature thermosensor TRPM8 is a non-selective cation channel, widely expressed in peripheral sensory neurons having their soma in the dorsal root (DRG) and trigeminal (TG) ganglia, but also in different organs and tumor malignancies." (PMID 35269831, 2022). "β-Lactams 24a and 29a display antitumor activity in different human tumor cell lines (micromolar potencies, A549, HT29, PSN1), but correlation with TRPM8 expression could not be established." (PMID 32843690, 2020).